KEAP1 (kelch like ECH associated protein 1)
Diseases named in the same sentence as KEAP1 in open-access papers (continued):
Sharing a sentence is not in itself a finding about the gene and the disease.
tumor (continued). "Nrf2 activity was found suppressed in tumor cells due to increased expression of the ubiquitin ligase Cul3 that, together with Keap1, targets Nrf2 for degradation by the proteasome." (PMID 24491031, 2014). "We evaluated the frequency of CUL3, RBX1, and KEAP1 disruption across multiple tumor types from the TCGA, selected based on data availability from TCGA (Section 2)." (PMID 25114896, 2014). "Our analysis on individual complex component genes revealed that, in addition to different frequencies of disruption, each tumor type displays a distinctive pattern of CUL3/KEAP1/RBX1 E3-ubiquitin ligase complex alterations." (PMID 25114896, 2014). "By hierarchical clustering, the expression of tumor associated antioxidants PPIA and Prdx6, and oxidative stress marker Nrf2 is more close to expression of Keap1." (PMID 24386210, 2013). "Along with increased NRF2 signaling, mutations in KEAP1 and NRF2 and constitutive expression of NRF2, are known to enable tumor cells to hijack the NRF2 pathway as a mechanism to resist chemotherapeutic agents." (PMID 23577226, 2013). "Compared with normal mucosa, the methylation of KEAP1 was more prominent in tumor tissues (P = 0.001)." (PMID 22325485, 2012). "Aberrant promoter methylation of KEAP1 was detected in 21/40 (53%) tumor tissues and 10/40 (25%) normal mucosal specimens." (PMID 22325485, 2012). "Although previous studies have shown that tumor tissue-based STK11, KEAP1, and CDKN2A/B mutations are adverse prognostic factors, we further confirm that ctDNA-based STK11, KEAP1, and CDKN2A can predict unfavorable outcomes in patients with non-metastatic NSCLC." (PMID 41491583, 2026). "Lastly, the mechanisms underlying the adverse prognostic impact of STK11, KEAP1, and CDKN2A mutations, currently inferred from tumor RNA-seq data and bioinformatic analyses, remain to be experimentally validated in future in vivo and in vitro fundamental research." (PMID 41491583, 2026). "We established a 3D multicellular tumor spheroid (MCT) model using murine N-HCC25 cells with CRISPR/Cas9-mediated knockouts of Nrf2 and its negative regulator Kelch-like ECH-associated protein 1 (Keap1), the latter mimicking constitutive activation." (PMID 41899867, 2026). "STK11 and KEAP1 mutations confer worse outcomes with immunotherapy among patients with KRASMUT but not among patients with KRASWT, provoking an accrual of neutrophils with T cell suppressive effects and tumor-promoting cytokines." (PMID 41009806, 2025). "This potential mechanism may involve SLC25A10’s disruption of ferroptosis in tumor cells through the regulation of the p62/KEAP1/Nrf2 pathway, thereby promoting the survival of tumor cells." (PMID 40393974, 2025). "Therefore, KEAP1 inactivation alone cannot confer tumor development or progression towards the SCC thyroid phenotype." (PMID 40600748, 2025). "Number of peripheral B cells was decreased in both WT and KEAP1-KO tumor-bearing mice, but the decrease was of a similar extent between WT and KEAP1-KO tumor-bearing mice, suggesting that the suppression of peripheral B cells in tumor-bearing mice is independent of the NRF2 activation in tumors." (PMID 41035689, 2025). "Additionally, immunofluorescence analysis demonstrated high HECTD2 and low KEAP1 expression in lenvatinib‐resistant tumor tissues." (PMID 39976163, 2025).
tumor (continued). "It is observed that Keap1 deletion promotes tumor aggressiveness and resistance while Keap1/NRF2 could serve as novel biomarker to predict the efficacy of therapeutic strategies." (PMID 40075700, 2025). "Here we provide direct evidence of derivation of SCC of the thyroid from PTC, based on a unique combination of likely pathogenic mutations in KEAP1, STK11 (LKB1), and RB1 found in both tumor components, along with loss of one copy of chromosome 11 and additional somatic mutations in the SCC tumor." (PMID 40600748, 2025). "We further show that omaveloxolone similarly slows tumor growth in KEAP1-mutant tumors." (PMID 41462606, 2025). "The expression and mutation profiles of IFNG, KEAP1, and PHKG2 may serve as indicators of the tumor mutational burden (TMB) in OV, indicating their potential utility as predictive biomarkers for tumor response and prognosis." (PMID 40744688, 2025). "Furthermore, co-mutations in KEAP1, a gene involved in regulating the antioxidant response, are also commonly seen in KRAS-mutant tumours." (PMID 40556802, 2025). "Mutations in KEAP1 lead to uncontrolled activation of NRFE2L2, which targets genes involved in xenobiotic biotransformation reactions and antioxidant metabolism, thereby protecting tumour cells from the effects of cytotoxic chemotherapy." (PMID 40650126, 2025). "In this system, the proto-oncogene EMSY was stabilized in kelch like ECH associated protein 1 (KEAP1) mutant tumors, which in turn inhibited homologous recombination repair (HRR), causing high tumor mutational burden that would normally be expected to foster type I IFN induction." (PMID 40098954, 2025). "Their abundance and surface marker expression in the KEAP1 KO tumor microenvironment may aid in tumor progression, possibly through different mechanisms and subtypes." (PMID 41462606, 2025). "Tumor cells effectively maintain the intracellular antioxidant state through Nrf2 activation as a result of mutations in genes such as NRF2, KEAP1, and CUL3, which accelerate tumor cell growth and contribute to the development of resistance to anti-tumor drugs." (PMID 40544155, 2025). "Taken together with the flow cytometric analyses, these results lead us to the hypothesis that immune cell infiltration into 3LL syngeneic tumor tissues is abrogated or heavily reduced in the KEAP1-KO tumors harboring high-level NRF2 activation." (PMID 41035689, 2025). "Interestingly, KEAP1/STK11 co-mutations occurred more frequently than KRAS/KEAP1 or KRAS/STK11 co-mutations, suggesting a functional synergy between NRF2- and LKB1-regulated pathways in tumor progression." (PMID 40427178, 2025). "However, rapid tumor progression was observed upon transplanting tumor cells from Keap1 knockout mice into wild-type mice." (PMID 40242036, 2025). "Taken together, the flow cytometry analyses of the immune cells in the 3LL transplanted tumors revealed that the infiltration of overall immune cells except for T cells into the tumor microenvironments was severely suppressed in NRF2-activated 3LL tumors due to KEAP1 deletion." (PMID 41035689, 2025). "Thus, P62 can regulate oxidative stress levels in tumor cells via modulating the Keap1-Nrf2 pathway." (PMID 40530331, 2025).
tumor (continued). "Characterizing a tumor’s specific redox signature—through genetic sequencing of KEAP1/NRF2, immunohistochemistry for antioxidant proteins, or advanced imaging probes that can non-invasively map redox states—is essential for selecting the right patients for the right therapy." (PMID 41154495, 2025). "This interaction promotes the targeted degradation of Nrf2 in tumor cells harboring KEAP1 mutations, thereby sparing Nrf2 in normal cells with wild-type KEAP1." (PMID 40422216, 2025). "In recent published in vivo studies, FBXW7 and KEAP1 were suggested to confer immune checkpoint blockade by alternating tumor microenvironment instead of directly modifying the tumor, through the way of decreasing T-cell infiltration and downregulating IFN-γ signaling, respectively." (PMID 41195266, 2025). "Following the degradation, mutation, or downregulation of the KEAP1 protein, NRF2 may translocate into the nucleus, conferring a survival advantage to tumor cells." (PMID 39744483, 2025). "Finally, the subcutaneous tumor formation experiments in nude mice using the H1975 wildtype and KEAP1-knockdown cells further confirmed that the sensitivity of NSCLC cells to the AURKA inhibitor MLN8237 was significantly enhanced after KEAP1 knockdown." (PMID 38521813, 2024). "Therefore, a correlation between the genotype distribution of rs35652124, rs3706649, rs6721961 of NRF2 and rs1048290 of KEAP1 in the three different types of tissues (blood, surrounding benign and tumour tissues) was performed." (PMID 39001473, 2024). "Also, the FGF families of the FGF-FGFR pathway and KEAP1 of the KEAP1-Nrf2 pathway, which acts on tumor growth and chemo-/radiation-resistance, were downregulated by these two glutaraldehyde-like compounds." (PMID 38674064, 2024). "Taken together, our data provided compelling evidence that KEAP1 enhances the efficacy of anti-PD-L1 tumor immunotherapy, suggesting that KEAP1 may hold promise as a potential treatment target." (PMID 38413563, 2024). "Notable decreased cytokines in the KEAP1-KO clones included IL-7R alpha, IL-18, IL-23, IL-31, and IL-33, which are pro-inflammatory and correlate with infiltration and activation of T cells and anti-tumor responses." (PMID 38542481, 2024). "Moreover, the combination of elevated KEAP1 expression with anti-PD-L1 immunotherapy resulted in a synergistic effect on both tumor growth and cytotoxic T-cell activation." (PMID 38413563, 2024). "In summary, using complementary methods, including ExCITE-seq and functional flow cytometry assays, we established that DRP-104 not only targets tumor-intrinsic purine metabolism but also diminishes Tregs and exhausted T cell populations that characterize Keap1 mutant lung tumors." (PMID 38536921, 2024). "As a result, we speculate that the tumor microenvironment of KEAP1 mutant tumors could be enriched with DON, the active form of DRP-104." (PMID 38536921, 2024). "The Keap1-Nrf2 signalling pathway plays a role in regulating oxidative stress in tumours." (PMID 38732643, 2024). "We hypothesize that KEAP1-mutant tumors are recruiting macrophages to the tumor with an initial M1-like phenotype, but the cytokine and chemical milieu of the microenvironment subsequently polarizes these cells to an M2-phenotype." (PMID 38542481, 2024).
tumor (continued). "As a multifunctional scaffold protein, Sequestosome1 could bind to Keap1 and inhibits Keap1 from binding to NFE2L2 that is newly synthesized during tumor ferroptosis." (PMID 39877159, 2024). "In HCC, TRIM25 enhances tumor cell survival by targeting Keap1 for degradation." (PMID 38199981, 2024). "In these contexts, the growth and the progression of SCLC was demonstrated to be related to the well-known molecular KEAP1/NRF2 axis, a master regulator of antioxidants and cellular stress responses, also implicated in the resistance of tumor cells against chemo- and radiotherapies." (PMID 38791966, 2024). "Caspase-3/-8/-9 and Keap1 levels were regulated, suggesting that the nano-carrier may induce tumor cell apoptosis damage by mediating Nrf2 or Keap1." (PMID 38792244, 2024). "Mutations of Kelch-like ECH-associated protein 1 (KEAP1) or Nuclear factor erythroid 2-related factor 2 (NFE2L2/NRF2) lead to an activated KEAP1/NFE2L2 pathway in NSCLC, resulting in a discrete tumor phenotype with poor overall outcome and relative resistance to chemotherapy." (PMID 39528799, 2024). "To determine whether impaired nucleotide synthesis was responsible for the reduction in tumor growth induced by DRP-104, we investigated whether the addition of nucleosides could restore the proliferation in treated Keap1 mutant tumor cells." (PMID 38536921, 2024). "Additionally, a subset of patients with somatic STK11 and/or KEAP1 alterations, along with lower baseline circulating tumor DNA, also experienced this clinical benefit." (PMID 38611005, 2024). "Moreover, other groups demonstrated a correlation between promoter methylation, histone acetylation status of NFE2L2/KEAP-1 and the biological function of several tumor cells." (PMID 38666930, 2024). "We found a good separation of NRF2 gene signature score distribution between KEAP1 mutated group and KEAP1 wild type group (wilcox single sided test pvalue < 0.05), suggesting that KEAP1 mutation drives activation of NRF2 pathway in LUAD tumor." (PMID 38241355, 2024). "Our results also suggest that KEAP1 agonist might be a potential clinical drug to boost anti-tumor immunity and improve immunotherapies in NSCLC." (PMID 38413563, 2024). "However, mutant-type KEAP1 had a more obvious suppression of the tumour immune microenvironment in LUADs than in LUSCs." (PMID 38962454, 2024). "KEAP1 and STK11 mutations are associated with positive survival impact in KRAS-WT tumours." (PMID 36864508, 2023). "An NRF2 mutation could disrupt the weak binding of Keap1 with the NRF2-DLG motif and activate NRF2 to promote tumor progression." (PMID 36644231, 2023). "In addition, KEAP1 and STK11 LOF mutations have both been linked to immune evasion by reducing the number of tumour-infiltrating lymphocytes (TILs) within the TME." (PMID 36864508, 2023). "Histologically, SMARCA4-DTS is a poorly differentiated tumor with rhabdoid or epithelioid features that can be distinguished from other soft tissue, and thoracic sarcomas by a higher tumor mutation burden (TMB) and the presence of smoking signatures, including KRAS, STK11, and KEAP1 mutations." (PMID 37378131, 2023). "However, compared with unmutated Keap1, K39R mutant Keap1 promoted the formation of Cullin3 ubiquitin ligase and increased Nrf2 ubiquitination, which eventually increased the production of ROS and inhibited tumor growth." (PMID 38259518, 2023). "Our data identify KEAP1 as a potential tumor suppressor through its control of NRF2." (PMID 37660919, 2023).
tumor (continued). "Taking together, these data indicated that SETD6 may participate in the process of apoptosis and oxidative stress of LUAD cells through NF-κB and Keap1/Nrf2 pathway, thus affecting the development of tumor." (PMID 36604642, 2023). "Different mechanisms can lead to aberrant sustained activation of NRF2 signalling in tumour cells, including somatic mutations in NFE2L2 or KEAP1, exon 2 skipping in NFE2L2, KEAP1 downregulation due to promoter hypermethylation, and transcriptional activation of NFE2L2 gene." (PMID 37373496, 2023). "RNS may disrupt the Keap1‐Nrf2 complex which can prolong the activation of Nrf2 and promote the antioxidant state inducing survival of tumour cells." (PMID 35961680, 2023). "At the same time, it has been found that Keap1 mutations lead to impairment of the Nrf2-Keap1-ARE signaling pathway, affecting its binding to Nrf2, causing a large accumulation of Nrf2, and increasing the resistance of tumor cells." (PMID 37359553, 2023). "In vivo, G6PD impairment significantly inhibits KEAP1 mutant tumor growth." (PMID 36843949, 2023). "Interestingly, a combination of cisplatin and CB-839 preferentially killed Keap1 wild-type (Cal33), Keap1 mutant (SSC9), and Keap1/Nrf2 mutant patients’ tumor cells." (PMID 37894373, 2023). "As the KEAP1 /Nrf2 axis had cellular protective effects on the antioxidant and detoxification activities, inhibiting Nrf2 undoubtedly aggravated the oxidative burden of tumor cells." (PMID 36700470, 2022). "It is worth mentioning that RBM10, KEAP1 and LRP1B, regarded as tumor suppressor genes, were more frequently mutated in aged group compared with young group, which may contribute to the high incidence of LUAD in the elderly." (PMID 35371328, 2022). "The administration of PARP inhibitors had anti-tumor efficacy in KEAP1 mutant NSCLC and this was further augmented with the addition of STING agonist, providing a rationale for the use of PARP inhibitors in NSCLC with BRCAness phenotype due to the KEAP1 mutation." (PMID 36358724, 2022). "Then, xenograft tumours were subjected to histopathological examination by routine haematoxylin–eosin (HE) staining, followed by immunohistochemical staining with antibodies against Keap1 and PTEN." (PMID 36142252, 2022). "Besides the effects of hypermethylation, the Keap1 expression can be affected by several microRNAs that act as oncogenes or tumor suppressor-microRNAs in tumor cells." (PMID 35773670, 2022). "To evaluate the loss of Keap1 and its effects on Nrf2 overexpression and cellular localization in primary HNSCC tumors, we immunoassayed Nrf2 expression using the anti-Nrf2 antibody in HNSCC primary tumor tissues." (PMID 35945195, 2022). "Importantly, the expressions of OTUD1 and KEAP1 were significantly correlated in the normal kidney cortex; however, the positive correlation was lost in the tumor." (PMID 35941131, 2022). "Supporting this speculation, we observed that the levels of Bap1 and Keap1 mRNA were progressively decreased in the lung tissues of KrasG12D/+ mice, compared with those of wild-type littermates during tumor progression." (PMID 35052618, 2022). "The Keap1/Nrf2/ARE system is traditionally considered a suppressor of tumor growth." (PMID 36547100, 2022). "Moreover, STK11 mutations often coexist with KEAP1 mutations that relate to cellular resistance to oxidative stress, and co-occurrence of KEAP1 mutations and PTEN inactivation is an indicator of an immunologically “cold” tumor." (PMID 36131239, 2022). "Secondly, if the RAS pathway was able to directly upregulate NRF2 expression, tumour development would not require somatic mutations in KEAP1 or NRF2 that abrogate the interaction between the two proteins." (PMID 36176767, 2022). "From these, it is inferable that Keap1 and Keap1β may function as more potent tumour promoters, albeit both isoforms were endowed with an intrinsic capability to inhibit hyper-active Nrf2 at preventing tumour development and malgrowth." (PMID 36142252, 2022).